CASP9 (caspase 9)
Diseases named in the same sentence as CASP9 in open-access papers (continued):
Sharing a sentence is not in itself a finding about the gene and the disease.
cancer (continued). "Due to the involvement of caspase-8 in extrinsic apoptosis pathway and caspase-9 in intrinsic apoptosis pathway, our results suggested that both extrinsic and intrinsic apoptosis pathway were participated in compound 3c-induced cancer cell death." (PMID 27625151, 2016). "We confirmed that COTI-2 treatment reduced phosphorylated-AKT and -caspase-9 in SHP-77 cells suggesting a role for it negatively modulating the PI3K/AKT/mTOR pathway in cancer cells." (PMID 27150056, 2016). "Previous studies have reported that TIIA can induce mitochondria-dependent apoptosis by regulating caspase-9 and Apaf-1 in several types of cancer." (PMID 25652794, 2015). "A549 and PC-9 cancer cells treated with two compounds in combination showed significant increase in caspase-9 and caspase-8 activities." (PMID 25799586, 2015). "AMF can also down-regulate caspase-9 and Apaf-1, making cancer cells more resistant to mitochondria-dependent apoptosis." (PMID 25652794, 2015). "Activation of caspase-9 has been observed by many authors in various types of cancer cells after taxane treatment and it usually appeared together with caspase-3 activation." (PMID 25685064, 2015). "In other cancers types, we also observed a change in the Bcl-2/Bax ratio with increase in cytochrome C and caspase 9 levels with PC treatment." (PMID 26499490, 2015). "The PTEN-AKT pathway plays an important role in cancer, and loss of PTEN function increases p-AKT levels, promoting the accumulation of caspase-9." (PMID 25886453, 2015). "Studies have shown that with exogenous stimulation, the expression of caspase-3, caspase-8 and caspase-9 in in vitro cultured cancer cells were increased." (PMID 25951128, 2015). "Our studies and others have demonstrated that adenovirus (Ad)-IL-24 induces apoptosis in cancer cells by activating caspase-9, poly (ADP ribose) polymerase (PARP), and JNK." (PMID 26009991, 2015). "We have recently reported that Ginsenoside Rh2 (G-Rh2) induces the activation of two initiator caspases, caspase-8 and caspase-9 in human cancer cells." (PMID 24622841, 2014). "The apoptotic effectors such as caspase 8, caspase 9 and caspase 3 were found to be upregulated besides DNA repair-associated enzyme, that is, PARP cleavage caused cancer cell death." (PMID 25299784, 2014). "Kuding tea significantly induced apoptosis in TCA8113 cancer cells (P<0.05) by upregulating Bax, caspase-3 and caspase-9 expression, and downregulating Bcl-2 expression." (PMID 24520272, 2014). "When cancer cells are exposed to anti-cancer drugs, changes in pro-apoptotic or anti-apoptotic molecules occur at the mitochondrial membrane, leading to activation of caspase-9." (PMID 25333266, 2014). "This suggests that the K30 induces apoptosis in cancer cells through intrinsic pathway where DNA damage leads to activation of caspase-9 that further contributes to the observed activities of caspase-3/7 and PS exposure." (PMID 24305113, 2013). "Activated Akt acts to phosphorylate Bad, Bax and caspase-9 or activate the NF-κB pathway to promote the resistance of cancer cells to apoptosis." (PMID 23420294, 2013). "In our previous studies, we demonstrated that caspase-2 was significantly activated (up to 20-fold) along with other caspases (caspase-3, caspase-9 and caspase-8) during apoptosis induction by taxanes in some cancer cells." (PMID 23672670, 2013). "Cassia tora L. significantly induced apoptosis in cancer cells (P<0.05) by upregulating Bax, caspase-3 and caspase-9, and by downregulating Bcl-2." (PMID 23426077, 2013). "In the group treated with U14 cells (cancer-induced group), the Bax, Bcl-2, caspase-3 and caspase-9 genes demonstrated significant changes." (PMID 23599733, 2013). "Anthricin treatment in both cancer cell lines promoted the time-dependent cleavage of caspase-3, caspase-7, or caspase-9." (PMID 23818925, 2013).
cancer (continued). "Third, several lines of in vitro evidence demonstrate that manuka induces death of cancer cells via the activation of caspase-9-dependent intrinsic apoptosis pathway." (PMID 23409104, 2013). "These combined data clearly suggest that spiclomazine activated caspase-9 specifically in both cancer cells through the intrinsic mitochondrial pathway, which was mediated by the loss of ΔΨm and the generation of ROS." (PMID 23840452, 2013). "It has been reported that SFN also induces apoptosis by mitochondrial-dependent pathways in some cancer cell lines, inducing loss of MMP and activating caspase-9, at concentrations ranging from moderate (6 μM) to high (25 μM)." (PMID 23662110, 2013). "It is possible that AA genotype of CASP9 Ex5+32G>A increases apoptosome activity which provides a protection from various disorders as well as cancer." (PMID 22616010, 2012). "In the cancer pathway cluster, CASP9 and PIK3R1 are both involved in 7 different cancer pathways, while SOS1 and TCF7L2 are both involved in 5 different pathways." (PMID 23281828, 2012). "Davallic acid, as shown in the present study, suppressed cell viability and induced apoptosis in the A549 cancer cells via increased ROS expression, enhanced release of cytochrome c, and induction of caspase-3, caspase-8, and caspase-9 expression." (PMID 23117433, 2012). "In conclusion, in this study we affirmed that davallic acid obtained from D. divaricata Blume induced cell death in lung A549 cancer cells, playing an important role in apoptosis induction via caspase-3, caspase-8, and caspase-9 activation." (PMID 23117433, 2012). "It has been reported that doxorubicin induces apoptosis by activating caspase-9 in cancer cells, we thus evaluated by fluorogenic assays caspase activity in MCF7 cells exposed to doxorubicin (3 μMol/L, 18 h)." (PMID 22217342, 2012). "PI3K/Akt signaling has been shown to be activated in a variety of cancers and activated Akt acts to phosphorylate Bad and Caspase-9 or activate NF-κB pathway to promote the resistance of cancer cells to apoptosis." (PMID 22408435, 2012). "Reduced protein levels of Apaf-1 or Caspase-9 or elevated expression of IAP family members have been found in a variety of cancer cell lines and primary tumor biopsy samples." (PMID 21611191, 2011). "These cancer-associated target mRNAs were connected to this network mainly through the interaction with apoptosis and cell death genes such as BCL2, CASP9 and ELK1." (PMID 21595958, 2011). "For example, numerous studies of human cancer have demonstrated that Apaf-1 or Caspase-9 are commonly reduced in cancer." (PMID 21611191, 2011). "Activated AKT and ERK1/2 phosphorylate proapoptotic mediators Bad and caspase-9, thereby inhibiting their proapoptotic actions and thus enhancing cancer cell survival." (PMID 21119656, 2011). "CXCL12 producing carcinomas cultured on poly-HEMA displayed heightened Bim and loss of Mcl-1 and Bcl-2 preceding cytochrome c release, and caspase-9 activation." (PMID 20877573, 2010). "As a first step, we examined activity levels of the extrinsic apoptotic initiator, caspase-8, and intrinsic apoptotic initiator caspase-9 levels in carcinoma cells secreting varying amounts of CXCL12 (Hi, Med, Low)." (PMID 20877573, 2010). "Alternatively, cancer cells grown in CM taken from the Surv-T34A cells began to apoptose through a caspase-2- and caspase-9-dependent pathway that was further enhanced by the addition of other chemo- and radiotherapeutic modalities." (PMID 19293795, 2009). "NK-NPT1 is cytotoxic and inhibited cancer cell proliferation (in vivo/in vitro) by inducing apoptosis involving Caspase 9 dependent Caspase 3 upregulation." (PMID 21593980, 2008). "E2F-1-induced cancer cell apoptosis was accompanied by Bax translocation from the cytosol to mitochondria and the induction of caspase-9 activity, suggesting that E2F-1-induced apoptosis is mediated by PUMA through the cytochrome C/Apaf-1-dependent pathway." (PMID 17263886, 2007).
cancer (continued). "Disrupting the BIR3 domain’s interaction with Caspase-9 or its antagonists could further amplify apoptotic signaling in cancer cells." (PMID 40076649, 2025). "In addition, studies have shown that ginsenoside CK can inhibit the activity of AKT1 in cancer cells, thereby increasing the expression levels of the apoptotic proteases Caspase-3, Caspase-8, and Caspase-9, and inducing apoptosis in cancer cells." (PMID 40422575, 2025). "Our findings that FN combined with anticancer drugs further upregulated the BAX/BCL-2 and cleaved caspase-9/caspase-9 ratios relative to drug treatment alone support the hypothesis that FN sensitizes cancer cells to apoptosis." (PMID 41614757, 2025). "Cancer cells were stratified based on apoptosis gene signatures and CASP9 expression." (PMID 41201629, 2025). "Similarly, SCY was also found to have induced caspase-9 cleavage in a time dependent manner after 24 h in both cancer cell lines, a process which in turn activated the executioner caspases-3 and -7." (PMID 40670819, 2025). "It has been discovered that the disruption of initiator caspase-8 and caspase-9 expression or function may play a role in the development or progression of cancer, and that their inactivation may increase resistance to existing therapeutic strategies." (PMID 40728967, 2025). "Quercetin could induce apoptosis via both intrinsic and extrinsic pathways by upregulating the expression of caspase-3, caspase-8, and caspase-9 in cancer cells." (PMID 40427691, 2025). "Cancer cells often exhibit elevated expression of Bcl-2 or Mcl-1, which stabilize the mitochondrial membrane and inhibit cytochrome C release, thereby blocking caspase-9 activation and the subsequent apoptotic cascade." (PMID 41375095, 2025). "In conclusion, the positive effect of EA on proapoptotic proteins such as CASP3 and CASP9 may trigger the death of cancer cells." (PMID 40405479, 2025). "However, after treatment with PTM, there was a significant increase in caspase-9 activity in the carcinoma cells." (PMID 40002856, 2025). "Further investigations revealed impaired mitochondrial functions through reduced mitochondrial membrane potential and increased caspase 3 and caspase 9 levels in carcinoma cells treated with the C2C12-EVs, suggesting mitochondrial-dependent apoptosis mediated by the intrinsic pathway." (PMID 41300368, 2025). "It is well known that ROS plays a central role during cancer progression where it participates in all cellular events (cell survival, growth, differentiation, protein synthesis and inflammation), therefore Caspase 9, Caspase 3, Bax, BCL2 and TBARS expressions were assessed." (PMID 38286826, 2024). "Together, Caspase 3, Caspase 8, and Caspase 9 play critical roles in mediating apoptotic cell death through both intrinsic and extrinsic pathways, highlighting their importance as therapeutic targets for cancer treatment." (PMID 38600497, 2024). "Effects of 6a, 6c and 6i hybrids on caspase-7 and caspase-9 levels in MCF-7 cancer cell line." (PMID 37165800, 2023).
cancer (continued). "The activation of caspase-9 further stimulates the activation of caspase-3, which orchestrates apoptosis by cleaving and activating proteins crucial for the proteolytic degradation of cancer cells." (PMID 37767520, 2023). "Caspases and their cleaved counterparts including cleaved caspase-3 and cleaved caspase-9 maybe involved in the induction of apoptosis as a possible method for cancer death to exert SHG-8’s therapeutic potential." (PMID 37869015, 2023). "Additionally, tumor suppressors caspase 8 (CASP8) and caspase 9 (CASP9) are phosphorylated by CDK1 facilitating apoptosis in cancer cells." (PMID 37311884, 2023). "CASP9 is an essential therapeutic target for various apoptosis‐related diseases, including cancer." (PMID 37849388, 2023). "Furthermore, berberine also noticeably enhanced apoptosis in cancer cells via activation of caspase-9 and -3 and induction of a higher ratio of Bax/Bcl-2 proteins." (PMID 36144625, 2022). "Additionally, quercetin also enhanced the expression of the pro-apoptotic proteins, Bid, cytochrome C expression in the cytoplasm and cleavage of caspase 9, which accelerated cancer cell death via apoptosis." (PMID 35811736, 2022). "Previous studies have shown that treating cancer cells with Ap increases caspase 9 expression." (PMID 35745733, 2022). "Ap treatment was accompanied by increased caspase 9 expression in cancer cells." (PMID 35745733, 2022). "TRIAP1 could bind to HSP70 in the cytoplasm and inhibit the formation of apoptosomes and caspase-9 activation, and had been shown to be upregulated in many types of cancers." (PMID 35109849, 2022). "Further studies have emphasized the role of CASP9 in translational medicine in cancer therapy." (PMID 36199443, 2022). "Similarly, upregulation of CASP9 through NF‐κB contributed to apoptosis activation in cancer cells, thus exerting the antitumour effect." (PMID 35233921, 2022). "Additionally, oleanolic acid as well as its isomer, ursolic acid, upregulated Bax and Caspase-9 genes and downregulated Bcl-2 in various cancer cells." (PMID 36077389, 2022). "On the other hand, JNK could induce cancer cell apoptosis by activating proapoptotic Bcl-2 proteins Bax and Bim that contribute to caspase-9 activation in the mitochondrial pathway." (PMID 38023774, 2022). "Apoptosis in cancer cells was accompanied by decreased mitochondrial membrane potential, the deregulated expression of mitochondrial proteins and the activation of caspase 9 and caspase 3, suggesting that rGO predominantly induced apoptosis via intrinsic pathway." (PMID 36012549, 2022). "The mechanism may be through the reduction of Ki67 and PCNA levels and inhibition of proliferation of cancer cells; The Caspase-3 and Caspase-9 promote the apoptosis of cancer cells; thereby inhibiting the ability of cancer cell invasion." (PMID 34482792, 2021). "Caspase 9 cell apoptotic pathway played a crucial role in the cancer stem cell elimination effects." (PMID 34890366, 2021). "They detected the highest value of the expression of anti-apoptosis genes Bcl-2 and livin in cancer cells compared with those co-cultured with T. spiralis E/S proteins and increased expression of pro-apoptosis genes Cyt-C, Apaf-1, caspase-9 and caspase-3 in the treated cancer cells." (PMID 33773560, 2021). "It was shown in the human breast cancer cell lines MCF-7 and MDA-MB-435 that SZ-685C compound selectively kills cancer cells via activation of both caspase-8- and caspase-9-based apoptotic pathways by suppressed whole or at least part of the Akt phosphorylation." (PMID 34440090, 2021). "Tumor cells can also hijack caspase-9 signaling to suppress radiation-induced immunity; deletion of caspase-9 or pharmacological pan-caspase inhibition with Emricasan can sensitize cancer cells to radiation therapy by rescuing type I interferon production in irradiated cells." (PMID 34305609, 2021).
cancer (continued). "LLF could enhance the expression of caspase-3 and caspase-9 in cancer cells, playing an inhibiting role on these cells." (PMID 33653412, 2021). "In addition, other studies have also found that ursolic acid downregulated the expression of Bcl-2 by activating caspase-3, caspase-8, and caspase-9, thereby inhibiting the proliferation of cancer cells and inducing apoptosis." (PMID 34194533, 2021). "ROS can also promote the activation of caspase-9, thus promoting the apoptosis of cancer cells." (PMID 33653412, 2021). "Caspase-9 activates apoptosis in cancer cells by disrupting the mitochondrial membrane potential." (PMID 35069196, 2021). "Moreover, melphalan upregulates expression of reactive oxygen species which in turn triggers apoptosis in cancer cells by activating caspase-9." (PMID 33773536, 2021). "By whole genome sequencing, we also found that RT-R-MDA-MB-231 cells harbor a nonsynonymous single nucleotide mutation in CASP9 (Arg173His; rs2308950), which is known to be involved in the pathogenesis of various cancers (data not shown)." (PMID 34066541, 2021). "The three clusters generated contained genes or proteins involved in apoptosis (BIRC3, BIRC5, PARP1, CASP8, and CASP9), transcriptional dysregulation in cancer (CDKN1B, RELA, CDKN1A, MYC, JUN, and MMP9), and cancer progression (CCND1, CASP3, CTNNB1, WNT1, and VEGFA) pathways." (PMID 34836311, 2021). "Therefore, this review discusses pros and cons of different approaches, such as ImmTAC, Herpes simplex virus thymidine kinase (HSV-TK), and inducible caspase-9 in cancer immunotherapy." (PMID 33859650, 2021). "Besides, the overexpression of the PI3K/Akt signaling pathway facilitates the depolymerization of Bcl-xl and Bcl-2, resulting in the inactivation of Caspase-9 and Caspase-3, and finally leads to the growth and proliferation of cancer cells." (PMID 32495637, 2020). "Such mitophagy defect may provoke cellular oxidative stress, energy metabolism imbalance, and calcium overload; consequently, it induces caspase 9-mediated intrinsic (mitochondrial) apoptosis and abolishes F-actin-dependent cellular migration in cancer cells." (PMID 32796618, 2020). "Its activation might promote the survival of cancer cells by phosphorylating and disabling significant proteins of the apoptotic pathway, including caspase-9 and Bad, and up-regulation of anti-apoptotic Bcl-2 family proteins." (PMID 32774810, 2020). "CK2 inhibits cancer cell apoptosis by blocking CASP9 cleavage and CAP8 activation." (PMID 33488754, 2020). "Based on the observations of the cleavage of caspase-9 prior to caspase-3, as well as the release of mitochondrial proteins to cytoplasm, mitochondria were assumed to be a primary target of Ur-A and Ur-C in cancer cells." (PMID 32555282, 2020). "Our results showed that the activity of caspases 8, 9 and 3/7 were all notablely increased in the cancer cell xenotransplanted zebrafish treated with Furanodiene, revealing that Furanodiene-induced zebrafish apoptosis are both caspase 8 and caspase 9 dependent, leading to cancer cell death." (PMID 30872660, 2019). "The mechanism by which this fraction decreasedthe A549 cell proliferation is thorough caspase activation, and the increasedactivity of caspase-3 and caspase-9 suggests that this fraction induces itscytotoxic effects in cancer cells via intrinsic apoptotic pathway." (PMID 31555336, 2019). "However, increasing evidence has shown that the failure to activate CASP9 under physiological and pathophysiological conditions can result in degenerative and developmental disorders and even cancer." (PMID 30886656, 2019). "Cytotoxic activity is executed via primary intracellular targeting of cancer cell mitochondria leading to cytotoxic ROS production as well as to AIF and cytochrome C release to cytoplasm, which results in caspase-9 and -3 activation and ultimately leads to apoptotic death of cancer cells." (PMID 31671612, 2019).